STAT4 (signal transducer and activator of transcription 4)
Diseases named in the same sentence as STAT4 in open-access papers (continued):
Sharing a sentence is not in itself a finding about the gene and the disease.
breast carcinoma (23 papers, 2016 to 2025). "The current investigation discovered that elevated STAT4 expression is associated with a favourable prognosis in breast cancer." (PMID 41010015, 2025). "Studies have shown that impaired STAT4 activation is associated with the development and progression of lung, colorectal, hepatocellular, and breast cancers." (PMID 39337665, 2024). "In high Ki-67 L.I. breast cancer, high-level STAT4 expression was associated with shorter overall survival (OS) (p = 0.042)." (PMID 32580398, 2020). "Data analyses from The Cancer Genome Atlas (TCGA) indicate that high expression of the IL-12/STAT4 axis is associated with better survival rates in breast cancer patients, especially in more aggressive subtypes, while reduced STAT4 expression correlates with poorer prognoses." (PMID 40733498, 2025). "STAT4 rs10168266 was also associated with reduced breast cancer risk in females." (PMID 39597056, 2024). "Furthermore, logistic regression analysis revealed that rs4274624 (STAT4) is linked to an elevated risk of breast cancer, whereas STAT4 rs925847 is associated with a reduced risk of breast cancer." (PMID 39575235, 2024). "A study by Gooch, Christy, and Yee (2002) demonstrated that reduced STAT4 activation compromises the ability of IL-4 to induce apoptosis in breast cancer cells, thus favoring the survival and progression of malignant cells." (PMID 40733498, 2025). "In the present study, the presence of the HPV16 E6 oncogene reduced the expression of JAK2 and STAT4, which are key regulators of the immune response and cell proliferation, potentially negatively impacting breast cancer prognosis." (PMID 40733498, 2025). "In vivo animal investigations revealed that STAT4 overexpression reversed breast cancer cells’ resistance to radiation and decreased tumour development via increasing THRB expression." (PMID 41010015, 2025). "Overexpression of STAT4 promoted programmed cell death ligand 1 (PD‐L1) level via the STAT4‐related pathway: IL‐12R/JAK2–STAT3–STAT4/PD‐L1 feedback axis in breast cancer cell." (PMID 38107057, 2023). "A potential strategy to activate STAT4 to promote macrophage‐cytotoxic T‐cell interaction in breast cancer tumor environment seems promising." (PMID 38107057, 2023). "To unveil gene function of STAT4 in breast cancer cell lines in vitro, we first detected the mRNA and protein expression of STAT4 in several common breast cancer cell lines." (PMID 38107057, 2023). "Overexpressed STAT4 increased programmed cell death ligand 1 (PD‐L1) and major histocompatibility complex class II levels in breast cancer cells." (PMID 38107057, 2023). "Although its prognostic role and gene function have been reported in several carcinomas, the role of STAT4 in vitro and in vivo in breast cancer remains poorly understood." (PMID 38107057, 2023). "Here, we revealed the prognostic value of STAT4 in clinical cohorts of breast cancer and demonstrated the oncogenic role of STAT4 in breast cancer BT549 cells." (PMID 38107057, 2023). "CPT acts like IL-12 and causes the release of perforin from CD4+ T cells through the phosphorylation of the JAK2/STAT4 pathway, mainly inhibited the growth of breast cancer cells." (PMID 36188552, 2022). "It was reported that STAT4 mRNA or protein was highly expressed in breast cancer, lung cancer, colorectal cancer." (PMID 35136014, 2022). "HBXIP can act as a transactivator by activating certain genes including c-Myc, E2F1, STAT4, and Sp1 to play a crucial role in the progression of breast cancer." (PMID 32850453, 2020). "Overexpression of STAT4 mRNA was significantly associated with a favorable OS (HR =0.79 (0.64–0.98), P=0.035), RPS (HR =0.69 (0.62–0.77), P<0.001) for breast cancer patients." (PMID 29326301, 2018). "Our results indicated that high STAT4 mRNA expression was significantly associated with favorable OS and RFS in breast cancer patients." (PMID 29326301, 2018).
breast carcinoma (continued). "Our results indicated that STAT3, STAT4, STAT5a, STAT5b, and STAT6 were significantly associated with favorable OS in breast cancer patients, especially for high pathological grade patients." (PMID 29326301, 2018). "The roles of SPIB and STAT4 in breast cancer, while not fully elucidated, were both associated with improved immune cell activity and better overall survival in previous studies." (PMID 40723262, 2025). "This indicates that JCHAIN may inhibit the proliferation and migration of breast cancer cells by affecting IL-2 and STAT4." (PMID 41010015, 2025). "At the same time, cell experiments found that JCHAIN may inhibit breast cancer cell proliferation, migration, and invasion through IL-2/STAT4." (PMID 41010015, 2025). "Also, high expression of STAT4 remarkably improves the survival rate of patients with breast cancer, especially in aggressive breast cancer subtypes." (PMID 38737443, 2024). "Several clinical breast cancer cohorts confirmed STAT4 as a T‐cell relevant prognostic biomarker." (PMID 38107057, 2023). "Schematic illustration of the prognostic role and gene function of STAT4 in breast cancer." (PMID 38107057, 2023). "In breast cancer subtypes, STAT4 was higher in HER2+ samples than in ER+ and TNBC patients." (PMID 38107057, 2023). "However, further evidences are needed in STAT4‐high expression cell lines and genome editing animal models to fully understand the role of STAT4 in breast cancer." (PMID 38107057, 2023). "However, the gene function and prognostic role of STAT4 in breast cancer remain poorly understood, particularly in TNBC." (PMID 38107057, 2023). "However, high levels of STAT4 expression predict better prognosis in breast cancer, hepatocellular carcinoma, and gastric cancer." (PMID 34276757, 2021). "Similar to STAT2, the evidence of STAT4 expression in breast cancer patients was limited." (PMID 29326301, 2018). "STAT4 expression was also stimulated with an increase in cytotoxic CD4+ T cell numbers, boosting its anti-breast cancer action." (PMID 41010015, 2025). "Both STAT3 and STAT4 were responsible for the transcription of IL12RB1 and IL12RB2 in breast cancer cell." (PMID 38107057, 2023). "A strong correlation between STAT4 and CD274 was unmasked in clinical single‐cell dataset GSE176078 and TCGA–breast invasive carcinoma (BRCA) cohort, and in breast cancer cell lines." (PMID 38107057, 2023). "STAT4 was found to be an excellent prognostic biomarker in HER2+ and Basal‐like subgroups of breast cancer cohort." (PMID 38107057, 2023). "To further investigate the role of STAT4‐related pathway in tumor environment following anti‐PD1 treatment, we analyzed the single‐cell dataset of breast cancers treated with anti‐PD‐1 immunotherapy (cases = 29)." (PMID 38107057, 2023). "One revealed mechanism is that STAT4 can activate the S100A4 promoter by interacting with HBXIP, which increases the expression of S100A4 and enhances the proliferation and migration of breast cancer cells." (PMID 30987235, 2019). "Recently, STAT4 indirectly modulated MHC‐I neoantigen presentation and CTL‐mediated anti‐tumor effect via KDM5D–AP1/2–MHC‐I pathway in colon cancer, however this mechanism is still unexplored in breast cancer." (PMID 38107057, 2023). "STAT4 is positively correlated with IFN‐γ in the breast cancer TME with or without anti‐PD‐1 treatment." (PMID 38107057, 2023). "STAT4 was hypothetically considered as a TME‐related gene and prognostic factor of breast cancer." (PMID 38107057, 2023). "Almost no STAT4 expression is detected in three of breast cancer cell lines, but MCF‐10A cells display high levels of STAT4 expression." (PMID 38107057, 2023). "Moreover, the PPI network uncovered the crucial roles of numerous proteins (e.g., FOXP3, STAT1, STAT4, FOXP3, JUN, and CD3D) in breast cancer." (PMID 36704358, 2022).
breast carcinoma (continued). "Bioinformatic analysis in breast cancer has shown that high expression of IL-12/STAT4 axis molecules, such as the IL-12 receptor genes (IL-12RB1 and IL-12RB2), STAT4, IFNγ, and TBX21, significantly increases the survival rates of patients with breast cancer, especially the more aggressive subtypes." (PMID 33076315, 2020). "STAT2, STAT4, STAT5a, STAT5b, and STAT6 had significantly favorable effect on RFS of breast cancer patients, but STAT1 had significant worse effect on RFS; STAT5b had significant favorable effect on PPS, while, STAT2 had significant worse effect on PPS for breast cancer patients." (PMID 29326301, 2018). "The regulons SPIB, STAT4, and ZMYND8 were seen as the master regulators of immune modulation in PRLR-low patients who did not experience early breast cancer events." (PMID 40723262, 2025).
Autoimmunity (22 papers, 2006 to 2025). The occurrence of an immune reaction against the organism's own cells or tissues. "Although most studies on STAT4 polymorphisms focus on autoimmunity, their potential role in HIV-1 infection warrants investigation, particularly in light of STAT4 involvement in Th1 differentiation and its regulation by SOCS3." (PMID 41009690, 2025). "For instance, the rs7574865 polymorphism of the STAT4 gene is a G > T change in the third intron, which has been associated with its TT polymorphic genotype with the increased presence of autoimmunity." (PMID 36980810, 2023). "To determine the role of STAT4 in SLE-associated Spt-AFC and Spt-GC responses and SLE-like autoimmunity development, we crossed STAT4−/− mice to the SLE-prone FcγRIIB−/− mouse strain (designated RIIB−/−.STAT4−/−)." (PMID 33446493, 2021). "Consistent with the genome-wide association studies data, STAT4 was shown to play an important role in autoimmune responses and autoimmunity development in SLE mouse models." (PMID 33446493, 2021). "STAT4- and T-bet–deficient mice are protected from autoimmunity associated with Th17 pathogenesis, suggesting Th1-related transcription factors play key roles in the pathogenicity of Th17 cells." (PMID 34806650, 2021). "The presence of variants in STAT4 genes has a major impact on the generation of autoimmunity." (PMID 36980810, 2023). "However, to our knowledge, no one has definitively demonstrated the effects of individual STAT4 risk alleles on autoimmunity development or cellular functions beyond association." (PMID 33446493, 2021). "Genetic risk factors have been newly identified for Sjögren’s syndrome, including IRF5, STAT4, CXCR5, IL12A, HLA-DRA, and BLK, which are linked to autoimmune disorders as well." (PMID 40136761, 2025). "Further studies in vivo and in vitro should focus on how the SNPs in STAT4 contribute to immune dysregulation and autoimmunity." (PMID 32226303, 2020). "Among these autoimmunity risk genes are IFN regulatory factor 5 (IRF5), which is involved in TLR signaling, and the signal transducer and activator of transcription 4 (STAT4) that interacts with the type I IFN receptor." (PMID 22066971, 2011). "Th1 produce IFN-γ and lymphotoxin-α under regulation by IL-12, which activates the lymphocyte transcription factor STAT4 (signal transducer and activator of transcription 4) and plays a significant role in the onset of autoimmunity." (PMID 16759382, 2006). "Despite the important role for STAT4 in SLE autoimmunity based on GWAS and mouse studies, how STAT4 may regulate autoimmune AFC, GC, and Tfh responses in SLE was previously not explored." (PMID 33446493, 2021). "STAT4 and IL23R are strongly involved in the control of the immune system through of the development and perpetuation of Th17 immune responses, which display a dominant role in autoimmunity-associated inflammation." (PMID 24312163, 2013). "Phosphorylated STAT4 leads to the production and activation of many downstream proinflammatory cytokines, which can contribute to the destruction of pancreatic beta cells and the autoimmunity seen in T1D." (PMID 23437231, 2013). "STAT4 and IL23R loci represent common susceptibility genetic factors in autoimmunity." (PMID 24312163, 2013). "Therefore, reduced activation of the IL-12/STAT4 cascade may be a potential mechanism for reduced autoimmunity and inflammation in NOD- Alox15null mice." (PMID 23437231, 2013). "Among them, STAT1 and STAT4 are directly involved in interferon and cytokine signaling, which are central to APS-related inflammation and autoimmunity." (PMID 40429780, 2025). "Together, these data indicate that STAT4 is largely dispensable for mounting autoimmune AFC, GC, and T cell responses and autoimmunity development in SLE-prone FcγRIIB−/− mice." (PMID 33446493, 2021).
Autoimmunity (continued). "There are some gene variants evaluated to be involved and are common in the pathogenesis of the four diseases of cytokine pathways (e.g., IRF5, STAT4, and TNFSF4) leading to the development of autoimmunity." (PMID 26339139, 2015). "Whether background genes in STAT4−/− mice or polygenic SLE models contribute to differential outcomes between our study and previous studies in identifying the role of STAT4 in promoting autoimmune responses and SLE autoimmunity remains to be resolved." (PMID 33446493, 2021). "In contrast, we found that STAT4 was not required for AFC, GC, and Tfh responses and autoimmunity development in this SLE model." (PMID 33446493, 2021).
hepatocellular carcinoma (20 papers, 2013 to 2024). A malignant tumor that arises from hepatocytes. "The STAT4 polymorphism rs7574865 has been extensively studied in the context of hepatocellular carcinoma (HCC) and chronic hepatitis B virus (HBV) infection." (PMID 39575235, 2024). "The STAT4 polymorphism rs7574865 has been associated with autoimmune and liver diseases, such as hepatocellular carcinoma (HCC), chronic hepatitis B (CHB), and liver cirrhosis (LC)." (PMID 38275379, 2023). "Previous reports demonstrate that decreased levels of STAT4 as indicative of worse prognoses in hepatocellular carcinoma, while high STAT4 expression has been linked to reduced tumor recurrence, and improved stage 3 prognosis in patients with gastric cancer." (PMID 32010142, 2019). "The influence of the STAT4 rs7574865 SNV was investigated as a cancer risk factor on the development of hepatocellular carcinoma (HCC)." (PMID 39337665, 2024). "This study provides novel evidence regarding the association of the STAT4 rs7574865 G > T single nucleotide polymorphism and hepatocellular carcinoma (HCC) within Latin American populations." (PMID 37760499, 2023). "Previous studies have shown that STAT4 plays a role in promoting apoptosis in hepatocellular carcinoma and ovarian granulosa cells." (PMID 36518671, 2022). "In addition, STAT4 SNVs are favorable prognostic markers for hepatocellular carcinoma and breast, gastric, and ovarian cancers." (PMID 39337665, 2024). "Moreover, in hepatoma cells, a decrease in STAT4 level indicates a poor prognosis of patients and an enhanced proliferative capacity of cancer cells." (PMID 38737443, 2024). "Notably, a tumor-suppressive function of STAT4 has been postulated for hepatocellular carcinoma as well as B-cell malignancies, being essential in cell cycle regulation and apoptosis induction." (PMID 37173993, 2023). "STAT4 seems to operate as a tumor suppressor in hepatocellular carcinoma (HCC)." (PMID 34638338, 2021). "However, the exact role of STAT4 in cancer remains unclear, STAT4 plays an opposite role in hepatocellular carcinoma, breast and gastric." (PMID 38294290, 2024). "However, the effects of genetic variants appear to be context-specific, such as significantly elevated STAT4 levels in the serum and peritumoral tissue of hepatocellular carcinoma (HCC) patients with the rs7574865 GG genotype." (PMID 39575235, 2024). "An immediate regulation of STAT4 by miR-141-3p via STAT4’s 3′UTR has been demonstrated by luciferase reporter assays in various cellular systems (e.g., hepatocellular carcinoma)." (PMID 37173993, 2023). "Moreover, previous studies showed that the MHC genes share a common influence on HBV infection, liver cirrhosis, hepatocellular carcinoma as well as associate with different risk in these outcomes; i.e. HLA-DQ, STAT4, C2, HLA-DRB1 for liver cirrhosis and HCC, HLA-DQ for CHB." (PMID 33736632, 2021). "In contrast, STAT4 showed the tumor suppressor effect in hepatocellular carcinoma (HCC) and was significantly correlated with Ki67 expression, histological grade, HBV infection, and tumor size in HCC clinical cohort." (PMID 38107057, 2023).